KIAA0586 (KIAA0586)
Description:
Required for ciliogenesis and sonic hedgehog/SHH signaling. Required for the centrosomal recruitment of RAB8A and for the targeting of centriole satellite proteins to centrosomes such as of PCM1. May play a role in early ciliogenesis in the disappearance of centriolar satellites that preceeds ciliary vesicle formation. Involved in regulation of cell intracellular organization. Involved in regulation of cell polarity (By similarity). Required for asymmetrical localization of CEP120 to daughter centrioles (By similarity).
Synonyms: TALPID3; JBTS23; SRTD14
Tractability: PROTAC: ubiquitination databases record sites on it.
Gene: Protein-coding gene on chromosome 14 (58,427,385 to 58,551,297, forward strand). Ensembl gene ENSG00000100578.
Subcellular location: Cytoplasm, cytoskeleton, microtubule organizing center, centrosome; Photoreceptor inner segment; Cytoplasm, cytoskeleton, microtubule organizing center, centrosome, centriole; Cytoplasm, cytoskeleton, cilium basal body
Gene Ontology:
Molecular function: protein binding
Biological process: cilium assembly; regulation of establishment of protein localization; smoothened signaling pathway
Cellular component: centrosome; ciliary basal body; photoreceptor inner segment; centriole
Genetic constraint (gnomAD): Loss-of-function variants: 51 observed, 66.56 expected, observed/expected ratio (o/e) 0.77, 90% interval 0.61 to 0.97. The upper end of that interval is the gene's LOEUF score, 0.97, which puts it in group 4 of 6, group 1 being the genes least tolerant of losing a copy. Missense variants: 1,063 observed, 1,090.8 expected, observed/expected ratio (o/e) 0.97, 90% interval 0.93 to 1.02. Synonymous variants: 369 observed, 375.12 expected, observed/expected ratio (o/e) 0.98, 90% interval 0.9 to 1.07.
Homologues: Orthologues: chimpanzee KIAA0586 (97% identical), macaque KIAA0586 (93% identical), dog KIAA0586 (78% identical), pig KIAA0586 (76% identical), rabbit KIAA0586 (75% identical), guinea pig KIAA0586 (72% identical), mouse 2700049A03Rik (69% identical), rat Kiaa0586 (69% identical), tropical clawed frog KIAA0586 (41% identical), zebrafish si:ch211-185a18.2 (31% identical).
Diseases named in the same sentence as KIAA0586 in open-access papers:
KIAA0586 is named in the same sentence as 32 diseases in open-access papers, as found by Europe PMC text mining. Sharing a sentence is not in itself a finding about the gene and the disease. The quoted sentences say what the papers report.
ciliopathies (30 papers, 2014 to 2025). "Here we report on the first Brazilian individual clinically diagnosed with hydrolethalus syndrome and molecular findings that instigate the discussion on the role of KIAA0586 as a causative gene of ciliopathies." (PMID 39063141, 2024). "Among 8 probands, we identified 12 variants in 7 genes associated with ciliopathies including Joubert syndrome (KIAA0586, ARMC4, BBS1, CEP83, ARMC9, TOGARAM1, WDR5)." (PMID 38585811, 2024). "KIAA0586 variants have been associated with a wide range of ciliopathies, mainly Joubert syndrome (JS, OMIM #616490) and short-rib thoracic dysplasia syndrome (SRTD, OMIM #616546)." (PMID 39063141, 2024). "KIAA0586 has previously been associated with recessive ciliopathy phenotypes in mouse, chicken and zebrafish." (PMID 26386247, 2015). "Variations in KIAA0586 could cause some different ciliopathies, such as one subtype of Joubert syndrome (JBTS23, OMIM #616,490), preaxial polydactyly and short rib thoracic dysplasia 14 (SRTD14; OMIM #616,546)." (PMID 36635699, 2023). "Variants in KIAA0586 could cause some different ciliopathies, including Joubert syndrome (JBTS), which is a clinically and genetically heterogeneous group of autosomal recessive neurological disorders." (PMID 36635699, 2023). "The HLHS candidate KIAA0586 was associated with ciliopathy as well as ID/DD." (PMID 35456433, 2022). "Comparison of clinical features of patients with KIAA0586 variants and other ciliopathies." (PMID 32080096, 2020). "It remains to be determined whether mutations in KIAA0586 can lead to other ciliopathies like Meckel–Gruber syndrome or nephronophthisis, which are often allelic to JS." (PMID 26026149, 2015). "Thus, it remains to be determined if KIAA0586 mutations are associated with other ciliopathy phenotypes or can lead to embryonic lethality." (PMID 26026149, 2015). "In addition to JBTS23, dysfunction of KIAA0586 may cause a more severe ciliopathy known as Short-rib thoracic dysplasia 14 with polydactyly (SRTD14; OMIM# 616546), a complex syndrome with skeletal and neurological manifestations." (PMID 32381069, 2020). "This case suggests a possible phenotypic expansion of KIAA0586‐related ciliopathy and supports a role for TALPID3 in human left‐right patterning." (PMID 41148001, 2025). "While a single case cannot definitively establish causality, this case suggests a potential phenotypic expansion of KIAA0586‐related ciliopathy that warrants further investigation." (PMID 41148001, 2025). "We also found that 67 HLHS-associated genes, 157 ciliopathy-associated genes and 3 genes associated with both (CCDC65, KIAA0586 and DNAH1) were connected via 841 intermediate interactors." (PMID 35456433, 2022). "By homozygosity mapping and whole-exome sequencing, we identified a novel locus, JBTS23, with a homozygous splice site mutation in KIAA0586 (alias TALPID3), a known lethal ciliopathy locus in model organisms." (PMID 26386247, 2015). "KIAA0586 mutations cause Joubert syndrome 23, a ciliopathy primarily affecting neurodevelopment, without reported laterality defects." (PMID 41148001, 2025). "Our patient showed a paternal inherited variant on KIAA0586, however, after an exome panel investigation for ciliopathies, we did not succeed in completely unraveling the molecular disarray." (PMID 39063141, 2024). "Besides KIAA0586, HYLS1 and KIF7 are also known for being causative of ciliopathies, indicating that all three genes may have similar or converging genomic pathways." (PMID 39063141, 2024).
ciliopathies (continued). "More severe ciliopathies with fetal lethality such as hydrolethalus syndrome (OMIM 236680), consisting of major hydrocephaly and brain malformations, and short-rib polydactyly (OMIM 616546), including skeletal dysplasia, have also been associated with causal KIAA0586 mutations." (PMID 29396404, 2018). "Human KIAA0586, also known as TALPID3, is a ciliopathy protein." (PMID 32366837, 2020). "Although KIAA0586 is not the first candidate gene for HLS, it is associated with ciliopathies." (PMID 39063141, 2024).
Joubert syndrome (21 papers, 2015 to 2025). Joubert syndrome (JS) is characterized by congenital malformation of the brainstem and agenesis or hypoplasia of the cerebellar vermis leading to an abnormal respiratory pattern, nystagmus, hypotonia, ataxia, and delay in achieving motor milestones. "We present a prenatal patient with suspected Joubert syndrome and left isomerism, carrying a likely pathogenic frameshift variant in KIAA0586, suggesting possible phenotypic expansion." (PMID 41148001, 2025). "Mutations in the human TALPID3 gene (KIAA0586) have been found in Joubert syndrome and Jeune asphyxiating thoracic dystrophy." (PMID 39682705, 2024). "With whole-exome sequencing (WES), we identified a novel 1.38-kb deletion and a single nucleotide variant (SNV) in KIAA0586 in a Joubert syndrome patient and confirmed them using Sanger sequencing in the family." (PMID 36635699, 2023). "WES revealed a splicing variant (NM_001244189.1: c.3303G > A) and a genomic region with a 1.38-kb deletion (NC_000014.9: g.58,926,242–58,927,621del) in KIAA0586 as causes of Joubert syndrome in a 9-month-old girl." (PMID 36635699, 2023). "KIAA0586 has been associated with Joubert syndrome, another condition associated with abnormal cerebellar development." (PMID 32963231, 2020). "Mutations in KIAA0586/TALPID3 (TA3) cause Joubert syndrome, in which 30% of affected individuals develop retinal involvement." (PMID 29396404, 2018). "They found that mutations in a gene encoding a protein called KIAA0586 also cause Joubert syndrome in humans." (PMID 26386247, 2015). "Recently KIAA0586 mutations have also been identified in Joubert syndrome patients." (PMID 35002618, 2021). "Although KIAA0586‐related Joubert syndrome is primarily neurodevelopmental, cilia also play a key role in left‐right axis formation, however, laterality defects have not been reported in this context." (PMID 41148001, 2025). "These comprise variants within genes associated with various types of human cancer (MAD1L1), Joubert syndrome 23 (KIAA0586), hair disorders (PADI3), mannose-binding lectin deficiency (MBL2), and multiple sclerosis (IL4R)." (PMID 36404349, 2023). "Although biallelic KIAA0586 variants cause Joubert syndrome, laterality defects have not been described in humans." (PMID 41148001, 2025).
hydrolethalus syndrome (3 papers, 2020 to 2024). Hydrolethalus (HLS) is a severe fetal malformation syndrome characterized by craniofacial dysmorphic features, central nervous system, cardiac, respiratory tract and limb abnormalities. "In this case report we discuss the first Brazilian individual clinically diagnosed with hydrolethalus syndrome and molecular findings that demonstrate the role of KIAA0586 as a causative gene of a group of genetic disorders." (PMID 39063141, 2024). "Some homozygous mutations of KIAA0586 have been shown to be embryonic lethal and to lead to severe developmental abnormalities such as Hydrolethalus syndrome and short-rib polydactyly." (PMID 35002618, 2021).
Joubert syndrome 23 (3 papers, 2021 to 2023). Any Joubert syndrome in which the cause of the disease is a mutation in the KIAA0586 gene. "The previously reported pathogenic variant in KIAA0586 (centrosomal protein homolog to chicken TALPID3) is the most frequently identified variant in Joubert syndrome type 23." (PMID 38318288, 2023).
retinal degeneration (3 papers, 2015 to 2024). Degeneration of the retina. "Nevertheless, patients with KIAA0586-related JBTS should be investigated for signs of retinal degeneration, and given that mutations in the JBTS gene CEP290 may cause non-syndromic Leber congenital amaurosis, KIAA0586 represents a candidate gene for isolated retinopathies." (PMID 26386247, 2015).
microcephaly (2 papers, 2021). A congenital or acquired developmental disorder in which the circumference of the head is smaller than normal for the person's age and sex. "Although in this study we excluded primary microcephaly and dysmorphies and obvious syndromes from the beginning, we found 4 syndromes, three of which were Joubert spectrum syndrome (No. 21, 25, and 27) due to pathogenic variants in TMEM237, LAMA, and KIAA0586, respectively." (PMID 34540776, 2021).
short rib-polydactyly syndrome (2 papers, 2014 to 2020). Short rib-polydactyly syndromes are a group of bone malformations characterized by a narrow thorax and polydactyly (usually preaxial). "We report two patients affected by short-rib polydactyly syndrome and overlapping phenotype with oral-facial-digital syndrome associated with the c.1815G>A variant in KIAA0586, suggesting a quite peculiar genotype–phenotype correlation." (PMID 32080096, 2020).
short-rib (1 paper, 2020). "KIAA0586 variants have been associated to short-rib thoracic dysplasia, an autosomal recessive skeletal ciliopathy characterized by a narrow thorax, short limbs, and radiological skeletal abnormalities." (PMID 32080096, 2020).
KIAA0586 also shares sentences with these, for which no sentence is quoted: cancer (3 papers); polycystic kidneys (3); polydactyly (3); Ataxia (2); holoprosencephaly (2); liver fibrosis (2); cholestasis (1); genetic disorders (1); hair disorders (1); hydrocephaly (1); Jeune asphyxiating thoracic dystrophy (1); Leber congenital amaurosis (1); liver failure (1); multiple sclerosis (1); nephronophthisis (1); neurological disorders (1); polymicrogyria (1); progressive ataxia (1); ptosis (1); retinal diseases (1); Retinal dystrophy (1); retinopathies (1); short-rib thoracic dysplasia 14 with polydactyly (1); skeletal dysplasia (1).